PGAP4 (post-GPI attachment to proteins GalNAc transferase 4)
Description:
Golgi-resident glycosylphosphatidylinositol (GPI)-N-acetylgalactosamine transferase that catalyzes the N-acetyl-beta-D-galactosamine transfer from an UDP-N-acetyl-alpha-D-galactosamine to the 4-OH-position of the first mannose of the glycosylphosphatidylinositol (GPI) of a GPI-anchored protein (GPI-AP). This modification occurs after the fatty acid remodeling step of the GPI-anchor maturation.
Synonyms: C9orf125; TMEM246; MGC12992
Tractability: Antibody: UniProt predicts a signal peptide or a membrane-spanning region. PROTAC: ubiquitination databases record sites on it.
Gene: Protein-coding gene on chromosome 9 (101,473,170 to 101,533,537, reverse strand). Ensembl gene ENSG00000165152.
Subcellular location: Golgi apparatus membrane
Subcellular location (Human Protein Atlas): Endoplasmic reticulum; Vesicles
Gene Ontology:
Molecular function: glycosyltransferase activity
Biological process: GPI anchor biosynthetic process
Cellular component: Golgi membrane
Genetic constraint (gnomAD): Loss-of-function variants: 12 observed, 29.92 expected, observed/expected ratio (o/e) 0.4, 90% interval 0.26 to 0.65. The upper end of that interval is the gene's LOEUF score, 0.65, which puts it in group 2 of 6, group 1 being the genes least tolerant of losing a copy. Missense variants: 425 observed, 538.11 expected, observed/expected ratio (o/e) 0.79, 90% interval 0.73 to 0.86. Synonymous variants: 205 observed, 224.45 expected, observed/expected ratio (o/e) 0.91, 90% interval 0.81 to 1.02.
Homologues: Orthologues: chimpanzee PGAP4 (100% identical), macaque PGAP4 (100% identical), pig PGAP4 (99% identical), mouse Pgap4 (98% identical), rat Pgap4 (98% identical), guinea pig PGAP4 (98% identical), dog PGAP4 (97% identical), tropical clawed frog pgap4 (46% identical), zebrafish pgap4 (41% identical), Caenorhabditis elegans F35C11.4 (20% identical).
Diseases named in the same sentence as PGAP4 in open-access papers:
PGAP4 is named in the same sentence as 1 disease in open-access papers, as found by Europe PMC text mining. Sharing a sentence is not in itself a finding about the gene and the disease.
PGAP4 shares sentences with these, for which no sentence is quoted: diabetes (1 paper).